AR (androgen receptor)
Diseases named in the same sentence as AR in open-access papers (continued):
Sharing a sentence is not in itself a finding about the gene and the disease.
tumor (continued). "In the LuCaP 35 tumor, both AR antibodies detected a similar 110 KDa AR polypeptide that corresponded to the size of ARFL." (PMID 22114732, 2011). "The effect of treatment with AR and mTOR inhibitors was compared with the addition of an mTOR inhibitor to bicalutamide therapy, as tumours progressed on the anti-androgens." (PMID 20842117, 2010). "Cholesterol in turn possibly contributes to androgen receptor signalling and thus castration resistant tumor growth in patients treated with androgen-deprivation therapy, by its conversion into androgens by metabolic enzymes." (PMID 21151972, 2010). "For example, Her2 overexpression was positively correlated with diminished sensitivity to androgen ablation, increased AR dependent PSA expression, increased AR activation, increased tumor mass and shortened tumor latency." (PMID 20126616, 2010). "Tumours in responders had the higher AR mRNA expression levels in pre neo-adjuvant chemotherapy condition (p < 0.02) which got reduced after neoadjuvant chemotherapy and the difference was found to be significant (P = 0.014)." (PMID 20831839, 2010). "In summary, our studies show that interaction between the AR and mTOR pathways appears to be involved in tumour progression in the xenograft models." (PMID 20842117, 2010). "Tumor cells were examined by flow cytometry for expression of estrogen receptor α, progesterone receptor, androgen receptor, her-2/neu, epithelial cell adhesion molecule, and CA125." (PMID 20356397, 2010). "Although the involvement of AR in tumor angiogenesis of PCa remains unsettled, several reports have suggested that angiogenesis can be independent of the AR." (PMID 21134280, 2010). "Autocrine production of growth factors or its receptors, activation of oncogenes and inhibition of tumor-suppressor genes are all possible mechanisms for bypassing the AR pathway." (PMID 20976069, 2010). "This study suggests that dual inhibition of AR and mTOR in castration-resistant xenograft models can restore sensitivity of tumours to anti-androgen therapy." (PMID 20842117, 2010). "The tumor expressed ER, PR, and AR by flow cytometry, with ER and PR confirmed by PCR (data not shown)." (PMID 20356397, 2010). "In the tumour stroma, the androgen receptor expression is inversely related to disease severity and outcome." (PMID 20808855, 2010). "Overall, the regulation of HIF-1α/HIF-1β and androgen receptor suggests a role of miR-101 in tumor progression and normal prostate development." (PMID 20478051, 2010). "Next, we assessed the potential of c-Met inhibitor in tumor formation of AR positive, androgen insensitive cells using an in vivo mouse model." (PMID 20946682, 2010). "In tumours treated with VN/124-1 in combination with everolimus, AR was markedly reduced and tumour growth inhibited." (PMID 20842117, 2010). "During neoplastic transformation of prostatic epithelial cells into tumour cells, expression of AR is retained by tumour cells, which is responsible for androgen-dependent tumour growth." (PMID 19888222, 2009). "Studies in animal models, PCa cell lines, and tumour specimens suggest that androgens modulate prostate growth and function through mechanisms that involve ‘cross-talk’ between androgen receptor (AR) and growth factor receptor signalling pathways." (PMID 19888222, 2009). "Significantly, tumour responses to abiraterone acetate were observed in castrate patients who had failed several prior lines of AR-targeting therapy (median of three prior hormonal therapies)." (PMID 19223900, 2009). "In the tissue array tested, the AR expressed at a much higher level in the tumor samples compared with the normal prostate tissues." (PMID 18218096, 2008). "Physiological levels of androgens inhibited the tumor cell growth and transformation mediated by the activation of the Wnt signaling and the AR overexpression." (PMID 18218096, 2008). "These tumor nodules were AR+ and p63+ with strong p-ERK and p-S6K activation but without detectable p-AKT." (PMID 19079609, 2008).
tumor (continued). "In fact, expression of the AR, Cyclin D1 and ErbB3 in normal adjacent tissue was found to be more informative than the corresponding tumor tissue in predicting PSA relapse in univariate models." (PMID 19025630, 2008). "The growth of tumors treated with AR-siRNA was very rapidly arrested, and after 10 days, the mean tumor volume represented only 15% of the control." (PMID 17925854, 2007). "Together, these results demonstrate that the main driver of the antitumoral effects of the AR-siRNA is the AR silencing in the tumor cells themselves." (PMID 17925854, 2007). "In patients, castration or AR antagonists affect not only the tumor cells, but also normal tissues, triggering deleterious side effects." (PMID 17925854, 2007). "Remarkably, it has been shown that one of the most common tumor-derived mutant forms of the AR, AR-T877A, is responsive to activation by BPA." (PMID 18007998, 2007). "The androgen receptor was expressed at constant levels in tumours from untreated mice (basal level at 0.32 a.u.)or from mice treated with docetaxel alone." (PMID 17211467, 2007). "Despite the initial success of therapy, recurrent tumours ultimately form wherein AR activity has been restored, and this event is typically preceded by a detectable rise in serum PSA." (PMID 17375037, 2007). "The staining pattern for AR was patchy in many of the tumors with proportion of tumor nuclei exhibiting immunopositivity for AR varying from 40–100%." (PMID 17020615, 2006). "Overall, AR expression is down-regulated in hormone-refractory prostate cancer but nearly 41.5% of tumor samples examined expressed some, albeit low (<10%) levels." (PMID 16859559, 2006). "In summary, AR immunoreactivity in 10% or more nuclei is consistent with AR positive tumor, which is strongly suggestive of breast and in some cases ovarian primary." (PMID 17020615, 2006). "Therapeutic targets include the adrenal steroid synthesis pathway, androgen receptor signalling, the epidermal growth factor receptor family, insulin growth factor-1 receptor, histone deacetylase, heat shock protein 90 and the tumour vasculature." (PMID 16983403, 2006). "Tumor growth is initially dependent on androgen levels, which stimulate cell proliferation and inhibit apoptosis via the androgen receptor (AR) pathway." (PMID 16608523, 2006). "Recent work revealed that androgen receptor (AR) expression is heterogeneous in cancer patients: individual patients can exhibit both AR-positive and AR-negative tumor populations." (PMID 16859559, 2006). "Significantly more tumours exhibited AR amplification following the development of hormone resistance (20%, 10 out of 49) compared to matched hormone-sensitive tumours from the same patient (2%, one out of 48) (P=0.0085)." (PMID 12888829, 2003). "This study examined androgen receptor (AR) gene amplification and protein expression in 102 matched paired hormone sensitive and resistant tumours from 51 patients." (PMID 12888829, 2003). "The level of AR expression was significantly higher in hormone-resistant tumours compared to matched hormone-sensitive tumours from the same patient (130, interquartile range, 55–167 vs 94.5 interquartile range, 55–120, P=0.019)." (PMID 12888829, 2003). "Androgen receptor gene amplifications are uncommon in hormone-sensitive tumours and are present in 20–30% of hormone-resistant tumours." (PMID 12888829, 2003). "AR expression has been reported to predict which patients will respond to hormone therapy and to correlate with tumour grade, stage and progression-free survival." (PMID 12888829, 2003). "These molecular signatures indicate a tumor phenotype that is highly dependent on the AR pathway." (PMID 41590376, 2026). "This suggests that the level of AR activity in tumors prior to ICB treatment may provide insights into preexisting tumor immune microenvironment and influence therapy selection." (PMID 41486951, 2026).
tumor (continued). "This altered chromatin state, driven by the absence of CHD1, enables the AR to bind to new genomic regions that are associated with pro‐oncogenic pathways, thus contributing to tumor development." (PMID 39853587, 2026). "This distinction is biologically significant, as recurrence mechanisms in advanced PCa—shaped by treatment-induced microenvironmental changes (e.g., hypoxia, androgen receptor alterations)—differ fundamentally from postoperative recurrence driven by residual tumor burden." (PMID 41590356, 2026). "Though enzalutamide, by invoking direct androgen receptor inhibition, and abiraterone, by blocking androgen biosynthesis, have early biochemical patterns which converge, especially during the hormone sensitive phase, when tumor androgen dependence prevails." (PMID 41517635, 2026). "Sex steroid hormones play a central modulatory role: estrogens, primarily via estrogen receptor β (ERβ), exert tumor-suppressive effects on colonic epithelium, whereas androgens promote pro-inflammatory and pro-tumorigenic signaling through androgen receptor (AR)-dependent pathways." (PMID 42274631, 2026). "Integrating longitudinal cfDNA methylomic profiles with phylogenetic reconstruction further revealed two resistance trajectories: one featuring high tumor heterogeneity with persistent AR signaling, and another marked by an AR-independent, stem-like program with metabolic reprogramming." (PMID 41674842, 2026). "Indeed, master regulator analysis of the two conditions identified that AR activity was reduced in tumor samples after treatment, confirming that enza inhibited AR activity in these patients." (PMID 41486951, 2026). "In summary, this study reveals a robust negative association between AR activity and both tumor immune infiltration and immunotherapy response across multiple tumor types, independent of sex." (PMID 41486951, 2026). "Here, we propose a testable framework in which therapeutic pressure increases tumor-intrinsic androgen receptor (AR) signaling, which may promote or reinforce a B7-H3-linked immune-excluded resistance program." (PMID 41958557, 2026). "Patients undergoing PCa treatment must be aware that PAEs can interfere with therapeutic efficacy; for instance, DBP may promote tumor progression by competitively binding to the AR or activating ERα, potentially undermining androgen deprivation therapy (ADT)." (PMID 41602838, 2026). "These agents exhibited superior anti-tumor efficacy compared with AR antagonists in vitro." (PMID 41492471, 2026). "Together, these findings reveal a robust, sex-independent negative association between AR activity and tumor immune infiltration and immunotherapy response." (PMID 41486951, 2026). "In addition, MED12 knockdown in prostate cancer cells inhibited expression of c-MYC and its downstream proliferation-related genes and reduced the AR-driven tumor growth." (PMID 40940746, 2025). "pioneered this effort by subdividing TNBC into four subtypes—basal-like 1 (BL1), basal-like 2 (BL2), mesenchymal (M), and luminal androgen receptor (LAR)—based on gene expression profiles and the influence of tumor-infiltrating lymphocytes and tumor-associated stromal cells." (PMID 40510158, 2025). "Notably, ARV-110 can effectively degrade both wild-type and mutant forms of AR, thereby inhibiting tumor growth even in cases of resistance." (PMID 39851497, 2025). "Furthermore, the PI3K/AKT signaling pathway can enhance the transcriptional activity of the androgen receptor, promoting tumor cell dependence on AR signaling." (PMID 40008000, 2025). "In addition, N-MYC amplification and AURKA overexpression cooperate to inhibit AR signaling and sustain tumor growth." (PMID 41264145, 2025). "When ER is expressed and active, AR blocks its activity, lowering the tumor cell growth." (PMID 40023399, 2025).
tumor (continued). "As a target of EVO, the AR can also induce tumor cell senescence, and AR-induced tumor cell senescence does not lead to the senescence-associated secretory phenotype (SASP) and its associated pro-cancer effects." (PMID 40729027, 2025). "The tumor cells tested positive for the androgen receptor, FOXA1, and GCDFP15." (PMID 40722519, 2025). "Mechanistically, AR directly binds AREs within promoter regions of MHC I-associated genes (e.g., HLA-A, B2M, TAP1/2), inhibiting their transcriptional activity and consequently diminishing tumor antigen presentation capacity." (PMID 41019050, 2025). "Although tumor grade showed a notable association with AR expression, this did not meet the Bonferroni-adjusted threshold for statistical significance." (PMID 40734715, 2025). "In xenograft models, EPI-001 downregulates AR target genes and inhibits tumor growth." (PMID 41020902, 2025). "Additionally, Carbidopa treatment has been shown to increase AHR protein levels while decreasing AR protein levels in tumor tissue." (PMID 40771930, 2025). "In addition to AR (+) cells, studies have found that the primary tumor contains AR cells (AR−/low), which exhibit innate resistance to treatment with androgen signaling inhibitors." (PMID 39711287, 2025). "Of note, in both cases tumor-bearing bones displayed upregulated Col1a1 and Fn1 levels compared with non-tumor-bearing bones, suggesting that differential response is due to intrinsic characteristics of each model, possibly influenced by AR signaling status." (PMID 40753365, 2025). "Furthermore, higher tumor expression of PTGES3 was correlated with worse overall survival in mCRPC patients treated with a first-line AR-targeted therapy (abiraterone, enzalutamide or apalutamide)." (PMID 41193657, 2025). "Upregulation of AR and a greater distribution into cytoplasm (≥20%) were associated with poor progression in OSCC, consistent with in vitro studies, which demonstrated that AR suppression reduced tumor cell growth by inducing apoptosis." (PMID 41228208, 2025). "Additionally, the AR can also induce tumor cell senescence by regulating the expression of P21 and tumor protein 63 (P63)." (PMID 40729027, 2025). "One can hypothesize that this could be due to effects of androgen deprivation in other cell types within the tumor that perhaps benefit from pro-androgenic activities despite androgen receptor overdrive." (PMID 40647555, 2025). "Patients diagnosed with a tumor in this latter group could potentially benefit from therapeutic approaches targeting AR." (PMID 41228208, 2025). "However, in AR-positive tumors, it is likely that AR status plays a role in the differential effect of RhoB as a tumor suppressor vs. tumor promoter." (PMID 41301045, 2025). "Additionally, our data revealed that AR positivity was more prevalent in well-differentiated tumor types." (PMID 40734715, 2025). "However, their usage prolongs the progression-free survival for approximately 3–5 years, whereby the selection of resistant cells and changes in the androgen receptor leads to resistant tumour cells." (PMID 40427006, 2025). "Furthermore, this compound suppressed the secretion of prostate-specific antigen (PSA), a tumor marker regulated by AR." (PMID 41465509, 2025). "ADT reduces androgen levels or inhibits AR function, leading to tumor regression in many cases." (PMID 40563466, 2025). "Notably, CW069 treatment resulted in a greater decrease (~ 4 fold) in tumor volume in mice bearing AR-TNBC tumors than in those with AR + TNBC (~ 1.5 fold;." (PMID 40448099, 2025). "Similarly, the prolonged activation of the LTF danger signal mirrors mechanisms observed in CRPC progression, where chronic NF-κB activation prevents tumor regression through AR/cyclin D1 maintenance." (PMID 40607016, 2025). "Studies have found that PSA is negatively correlated with tumor progression at the mRNA level, which may be related to the reduced AR signaling during tumor progression." (PMID 39711287, 2025).
tumor (continued). "AR's role varies across different tumor types and even among subtypes of the same tumor." (PMID 40583627, 2025). "In addition to tumor-inherent androgen signaling, myeloid cells themselves also express functional AR." (PMID 41488638, 2025). "It was also shown that the AR blockade with antiandrogens such as enzalutamide may inhibit DNA repair, rendering tumor cells more sensitive to radiotherapy-induced damage." (PMID 40150035, 2025). "In particular, basal-like immune suppressive (BLIS), mesenchymal (MES), and luminal androgen receptor (LAR) subtypes showed lower levels of tumor infiltrating lymphocytes and suppressive immune signatures, which contribute to their reduced responsiveness to immunotherapy." (PMID 40783751, 2025). "In our study, most AVPC samples were characterized by high expression of AR and other AC markers, indicating that aberrant AR pathway activation might still be the main driver of tumor growth." (PMID 40181402, 2025). "Targeted therapies work by specifically blocking key molecular pathways that drive tumor growth and metastatic, including androgen receptor-targeted therapy, DNA damage response-targeted therapy, prostate-specific membrane antigen-targeted therapy, bone microenvironment-targeted therapy." (PMID 41200193, 2025). "Both LMO2 and CCL5 promote tumor cell AR signaling reactivation via paracrine signaling." (PMID 41154598, 2025). "This suggests that AR might play different roles depending on the stage of BC, potentially promoting tumor initiation but inhibiting progression." (PMID 40361239, 2025). "Some reports indicate that AR is a tumor suppressor, while others demonstrate a tumor supportive role for AR, particularly when the percent of cells positive for AR in a tumor is more than 2 times that of ER, and in the context of tamoxifen and AI therapy resistance." (PMID 41216931, 2025). "Elevated levels of androgens may contribute to the aggressiveness of OSCC, corroborated by studies linking heightened AR expression to advanced tumor stages." (PMID 40608705, 2025). "One plausible explanation is the development of neuroendocrine differentiation or AR-independent tumor clones, which may contribute to tumor growth and progression despite androgen deprivation and profound PSA responses." (PMID 41470112, 2025). "sAREs seem to drive differentiation and are potentially tumor suppressive in early-stage disease, as inability to activate an sARE leads to incomplete virilization in male mice and produces a more oncogenic AR." (PMID 39858088, 2025). "Similarly, in LNCaP xenograft tumours, compared with those in normal tumours, the protein and mRNA levels of AR decreased in tumours that recurred after castration treatment, whereas the protein and mRNA levels of GR increased." (PMID 40759641, 2025). "In addition, β-catenin can interact with other pathways (AR) to coordinate proliferation during tumor growth." (PMID 39917165, 2025). "In addition, oxidative stress can induce alternative pathways of AR activation, further promoting castration resistance and tumor progression 129-132." (PMID 41281744, 2025). "Additionally, AR can indirectly promote tumor progression by inhibiting the activity and stemness of infiltrating CD8+ T cells." (PMID 40583627, 2025). "Together, our findings indicate that localized PCas may be variably sensitive to HER2 inhibition or to combination AR and HER2 inhibition, depending upon the proportion of HER2-high/AR activity–low tumor cells contained therein." (PMID 40906535, 2025). "Recently, it was demonstrated that the binding patterns of AR in normal prostate cells on the target genes were significantly different as compared to tumor cells, highlighting a tumor suppressor role of AR in normal tissues, in contrast to a tumor-promoting role in cancer cells." (PMID 41228208, 2025). "Moreover, Gal-1 inhibition reduced tumor growth in both AR-positive and AR-negative xenograft models, indicating that its impact goes beyond AR signaling." (PMID 39941722, 2025).